LYZL4 (lysozyme like 4)
Description:
May be involved in fertilization (By similarity). Has no detectable bacteriolytic and lysozyme activities in vitro (By similarity).
Synonyms: LYC4; MGC26768; LYZA
Tractability: Antibody: UniProt places it where antibodies can reach, with medium confidence; UniProt predicts a signal peptide or a membrane-spanning region; its Gene Ontology location is reachable by antibodies, with medium confidence.
Gene: Protein-coding gene on chromosome 3 (42,397,083 to 42,410,610, reverse strand). Ensembl gene ENSG00000157093.
Subcellular location: Secreted; Cytoplasmic vesicle, secretory vesicle, acrosome; Cell projection, cilium, flagellum
Subcellular location (Human Protein Atlas): End piece; Principal piece; Predicted to be secreted
Gene Ontology:
Molecular function: lysozyme activity
Biological process: defense response to bacterium; fertilization; fusion of sperm to egg plasma membrane involved in single fertilization
Cellular component: nucleus; acrosomal vesicle; extracellular region; sperm flagellum; motile cilium
Genetic constraint (gnomAD): Loss-of-function variants: 9 observed, 13.16 expected, observed/expected ratio (o/e) 0.68, 90% interval 0.41 to 1.19. The upper end of that interval is the gene's LOEUF score, 1.19, which puts it in group 5 of 6, group 1 being the genes least tolerant of losing a copy. Missense variants: 147 observed, 157.75 expected, observed/expected ratio (o/e) 0.93, 90% interval 0.81 to 1.07. Synonymous variants: 54 observed, 55.6 expected, observed/expected ratio (o/e) 0.97, 90% interval 0.78 to 1.22.
Homologues: Orthologues: chimpanzee LYZL4 (99% identical), dog LYZL4 (82% identical), pig LYZL4 (79% identical), rabbit LYZL4 (78% identical), rat Lyzl4 (73% identical), macaque LYZL4 (72% identical), mouse Lyzl4 (70% identical), guinea pig LYZL4 (67% identical), Drosophila melanogaster CG8492 (34% identical), Drosophila melanogaster CG16756 (32% identical), Drosophila melanogaster CG30062 (30% identical), Drosophila melanogaster CG7798 (30% identical), and 8 more. Paralogues in human: SPACA3 (43% identical), LYZL6 (42% identical), LYZL1 (39% identical), LYZL2 (39% identical), LYZ (37% identical), SPACA5 (37% identical), SPACA5B (37% identical), LALBA (29% identical).
Diseases named in the same sentence as LYZL4 in open-access papers:
LYZL4 is named in the same sentence as 2 diseases in open-access papers, as found by Europe PMC text mining. Sharing a sentence is not in itself a finding about the gene and the disease. The quoted sentences say what the papers report.
Alzheimer disease (1 paper, 2025). A progressive, neurodegenerative disease characterized by loss of function and death of nerve cells in several areas of the brain leading to loss of cognitive function such as memory and language. "These novel insights position Lyzl4 as a promising therapeutic target for Alzheimer's disease, paving the way for further exploration into potential AD treatments." (PMID 39555667, 2025).
LYZL4 also shares sentences with these, for which no sentence is quoted: bacterial infections (1 paper).